PHYHIP (phytanoyl-CoA 2-hydroxylase interacting protein)
Description:
Its interaction with PHYH suggests a role in the development of the central system.
Synonyms: PAHXAP1; DYRK1AP3; KIAA0273; PAHX-AP
Tractability: PROTAC: its protein half-life has been measured.
Gene: Protein-coding gene on chromosome 8 (22,219,703 to 22,232,101, reverse strand). Ensembl gene ENSG00000168490.
Subcellular location (Human Protein Atlas): Mitochondria; Nucleoplasm
Gene Ontology:
Molecular function: protein binding; protein tyrosine kinase binding
Biological process: intracellular protein localization
Cellular component: cytoplasm; mitochondrion; nucleoplasm
Genetic constraint (gnomAD): Loss-of-function variants: 5 observed, 21.93 expected, observed/expected ratio (o/e) 0.23, 90% interval 0.12 to 0.48. The upper end of that interval is the gene's LOEUF score, 0.48, which puts it in group 2 of 6, group 1 being the genes least tolerant of losing a copy. Missense variants: 229 observed, 432.67 expected, observed/expected ratio (o/e) 0.53, 90% interval 0.47 to 0.59. Synonymous variants: 199 observed, 181.09 expected, observed/expected ratio (o/e) 1.1, 90% interval 0.98 to 1.24.
Homologues: Orthologues: chimpanzee PHYHIP (100% identical), guinea pig PHYHIP (100% identical), macaque PHYHIP (100% identical), rabbit PHYHIP (99% identical), mouse Phyhip (99% identical), pig PHYHIP (99% identical), rat Phyhip (99% identical), dog PHYHIP (99% identical), tropical clawed frog phyhip (70% identical), zebrafish phyhip (68% identical), Caenorhabditis elegans T10H4.4 (25% identical), Caenorhabditis elegans M01B2.12 (24% identical), and 4 more. Paralogues in human: PHYHIPL (76% identical).
Diseases named in the same sentence as PHYHIP in open-access papers:
PHYHIP is named in the same sentence as 7 diseases in open-access papers, as found by Europe PMC text mining. Sharing a sentence is not in itself a finding about the gene and the disease. The quoted sentences say what the papers report.
breast carcinoma (2 papers, 2021 to 2025). "Miyako Yamamoto experimentally demonstrated that PHYHIP is expressed at lower levels in breast cancer cell lines than in normal cells and that this gene may have an important relationship with breast cancer." (PMID 40869909, 2025). "The research of Fumiichiro Yamamoto and Miyako Yamamoto shows that The expression of PHYHIP in breast cancer cell lines and clinical cases is down-regulated, which may be related to the occurrence and development of breast cancer." (PMID 33692828, 2021).
cancer (3 papers, 2020 to 2025). A tumor composed of atypical neoplastic, often pleomorphic cells that invade other tissues. "In our study, PHYHIP was also used as a prognostic model for GBM cancers." (PMID 40869909, 2025).
tumor (2 papers, 2022 to 2025). "Representative protein expression of MEOX2, PHYHIP, RBBP8, ST18, TCF12, and THRB in tumor tissues was demonstrated based on immunohistochemical analysis in the HPA database." (PMID 40869909, 2025). "The genes with low expression in the tumor group were CRISP3, FAM3D, SCNN1B, CRISP2, RBM20, PHYHIP, C2orf54, SLC5A1, PTCRA, C15orf59, and ANO10." (PMID 35389773, 2022). "MEOX2 and PHYHIP, showed no significant protein expression in tumor tissues; the THRB showed “low intensity”, RBBP8 and ST18 showed “medium intensity”, and, interestingly, the TCF12 showed “high intensity”." (PMID 40869909, 2025).
PHYHIP also shares sentences with these, for which no sentence is quoted: gastric cancer (1 paper); glioblastoma multiforme (1); ichthyosis (1); laryngeal carcinoma (1).